CDKN2A (cyclin dependent kinase inhibitor 2A)
Diseases named in the same sentence as CDKN2A in open-access papers (continued):
Sharing a sentence is not in itself a finding about the gene and the disease.
meningioma (continued). "Furthermore, it has been demonstrated that meningiomas with homozygous CDKN2A/B deletions frequently harbor the loss of the methylthioadenosine phosphorylase (MTAP), which is in close proximity of the gene loci." (PMID 38017560, 2023). "In addition, CDKN2A/B HoDe was introduced as a criterion for upgrading meningiomas to grade 3, owing to its significant association with recurrence and shorter progression time." (PMID 37296907, 2023). "While Rb-deficiency (usually by way of an inactivating mutation) has been thought to be rare in meningiomas, increased CDKN2A mRNA expression may act as a transcriptomic signature for this alteration." (PMID 37093270, 2023). "However, their sample size was limited to 8 meningiomas with CDKN2A loss, 7 of which were already classified as WHO grade 3." (PMID 37093270, 2023). "Notably, a recent analysis of 776 meningiomas showed that even heterozygous deletion of CDKN2A/B was associated with a shorter time to recurrence, which was confirmed in another series of 1506 cases." (PMID 37296907, 2023). "Another part is related to the degree of tumor malignancy, such as the deletion of histone H3 K27me3 expression is closely associated with meningioma recurrence, TERT promoter mutation and CDKN2A/B pure deletion are molecular biological markers of CNS WHO grade 3 meningioma." (PMID 36969005, 2023). "In addition, pTERT mutations and CDKN2A/B HoDe identify only some meningiomas that are devoid of histological malignancy but are prone to recurrence." (PMID 37296907, 2023). "Indeed, CDKN2A serves as a useful biomarker for identification of meningiomas with a high risk of early recurrence." (PMID 37010677, 2023). "Similarly, in meningiomas CDKN2A homozygous loss is associated with anaplastic histology and with increased risk of recurrence or progression." (PMID 37138345, 2023). "A recent study proposed that p16 loss by IHC could sensitively detect CDKN2A loss in high-grade meningiomas." (PMID 37093270, 2023). "In this WHO classification, loss of H3K27me3 is indicative of aggressive meningioma behavior and recurrence, and homozygous deletions of CDKN2A/B and mutations of TERT promoter (pTERT) are criteria for Grade 3 meningiomas since they are linked to an increased risk of recurrence." (PMID 38001599, 2023). "In addition, also heterozygous loss, mutations, and promoter methylation of CDKN2A was found to be strongly related to recurrent meningiomas and a high Ki-67 index." (PMID 36181606, 2023). "Furthermore, heterozygous CDKN2A/B deletion (HR: 5.5, 95% CI 4.0–7.6, p < 0.00001) was also significantly associated with meningioma progression." (PMID 38017560, 2023). "Furthermore, a meningioma harboring either a TERT promotor mutation or homozygous deletion of CDKN2A/B is classified as a grade 3 anaplastic tumor, regardless of histologic grade." (PMID 35402234, 2022). "Meanwhile, Driver at al. incorporated 15 targeted, high-risk molecular alterations (13 chromosomal alterations and loss of CDKN2A/B) with histologic (presence of frequent mitoses) and clinical (extent of resection, tumor volume, and recurrence status) factors to stratify meningioma." (PMID 35402234, 2022). "A CDK inhibitor combined with ribociclib could be a potential treatment approach for meningiomas with mutations in the tumor-suppressor genes CDKN2A and CDKN2B (NCT02933736)." (PMID 35712491, 2022). "In addition to NF2 inactivation, loss of CDKN2A/B contributes to meningioma progression and has been associated with shorter time to recurrence in mice." (PMID 36686824, 2022). "Thus, CDKN2A/B status can provide a useful biomarker for the identification of meningioma patients with a high risk of early recurrence." (PMID 32642869, 2020).
meningioma (continued). "In contrast with other chromosomal alterations, the role of chromosome 9 in the development of malignant meningiomas is better defined, since it has been mostly associated with three tumor suppressor genes coded at chromosome 9p21: CDKN2A/p16INKa, CDKN2A/p14ARF and CDKN2B/p15ARF." (PMID 25965831, 2015). "Thus, we believe co-occurring mutations other than chromosome 1p loss, TERT mutation, CDKN2A/B loss can stratify NF2 mutated meningiomas, although a larger data set is required to confirm this hypothesis." (PMID 40562609, 2025). "The hypothesis of this study is that MTAP and p16 expression as assessed by IHC can act as reliable surrogate markers for detecting homozygous CDKN2A/B loss in meningiomas, providing a cost-effective alternative to more expensive and less accessible molecular techniques." (PMID 39409918, 2024). "In conclusion, this is the first study to show that immunostainings for MCM2 and ACADL may be useful for identifying atypical meningiomas characterized by higher genomic instability, CDKN2A HeDe, higher integrated molecular grade, recurrence risk, and shorter RFS." (PMID 37014425, 2023). "However, the fact that increased expression of CDKN2A has also been associated with poorer clinical outcomes in some cancers, including here in meningiomas, suggests that this relationship may be more complex." (PMID 37093270, 2023). "Notably, we also found that p16-positive regions of meningiomas with CDKN2A deletion still demonstrated the same CDKN2A loss detected in the bulk tumor, suggesting either a lack of specificity of p16 IHC or the nature of CDKN2A loss as a late, subclonal event in tumorigenesis." (PMID 37093270, 2023). "Group 3 meningiomas have the worst prognosis and high chromosomal instability and proliferation indices, show resistance to cytotoxic therapies, and may have pTERT mutations and/or CDKN2A/B deletion." (PMID 38001599, 2023). "Finally, meningiomas in the third group have a high chromosomal instability and proliferation index, may feature pTERT mutations and/or CDKN2A/B HoDe, have the worst prognosis, and are resistant to cytotoxic drugs." (PMID 37296907, 2023). "In 2002, deletions in chromosome 9p21, which includes the CDKN2A, CDKN2B and MTAP genes, were linked to malignant progression or anaplastic phenotype in meningiomas." (PMID 40227557, 2025). "The 2021 WHO Classification of CNS Tumors incorporates molecular criteria, including CDKN2A homozygous deletion and TERT promoter mutation, in the diagnosis of anaplastic (WHO grade 3) meningioma." (PMID 41497451, 2025). "In terms of clinical behavior, a few rare molecular alterations have been linked to aggressive meningioma biology, including oncogenic variants in the TERT promoter region and homozygous deletions of CDKN2A/CDKN2B." (PMID 40951339, 2025). "In meningioma, we identified focal prognostic regions on chromosomes 2q, 3q, 5p, 5q, 8p, 9p, 10q, 12q, 13q, and 14q, including a focal peak at the CDKN2A/B and interferon gene locus on 9p." (PMID 40603285, 2025). "FAP expression was more frequent in meningiomas of CNS WHO grade 3 (vs. CNS WHO 2; p < 0.001), and samples with NF2 mutations (p = 0.032) or CDKN2A/B deletions (p = 0.013) compared to wildtype." (PMID 39969538, 2025). "In a large series of over 1500 meningiomas, Wang and colleagues found that heterozygous CDKN2A/B deletion had an impact on outcome as adverse as CDKN2A homozygous deletion." (PMID 40227557, 2025). "In high-grade/progressive meningiomas, the NF2-associated genomic subclass frequently harbors CDKN2A/B alterations." (PMID 41487565, 2025). "Homozygous deletions of CDKN2A/B and oncogenic TERT promoter mutations are well-established independent adverse prognostic factors and defining features of CNS WHO grade 3 meningiomas." (PMID 40951339, 2025). "We identified anaplastic meningiomas with homozygous CDKN2A deletions but retained MTAP gene and MTAP protein expression." (PMID 40227557, 2025).
meningioma (continued). "This discrepancy can result in the missing of CDKN2A homozygous deletions and misgrading of meningiomas when MTAP IHC is used as a sole surrogate marker or when an inappropriate FISH probe is employed." (PMID 40227557, 2025). "In another series of 15 anaplastic meningioma, three tumors demonstrated a homozygous CDKN2A deletion, as shown by copy number variation (CNV) plots inferred from methylation analysis." (PMID 40227557, 2025). "A recent study revealed that CDKN2A mRNA expression acts as a biomarker of clinically invasive meningiomas, with potential therapeutic significance." (PMID 40426913, 2025). "Muti-factorial assessments, including mitotic count, CDKN2A/B status, and CNVs, can differentiate between aggressive WHO grade 1 and well-behaved WHO grade 2 meningiomas, which is useful for risk stratification." (PMID 38730704, 2024). "CDKN2A and CDKN2B have been associated with poorer prognosis in meningioma, acute lymphoblastic leukemia and lung adenocarcinoma." (PMID 39236081, 2024). "Biopsy revealed metastasis of the meningioma, now with 2.7 mitoses/mm2, necrosis and homozygous CDKN2A/B deletion, corresponding to an anaplastic CNS meningioma WHO grade 3." (PMID 38611589, 2024). "Additional Cdkn2a deletion (lost in a subset of high-grade meningiomas) leads to an increased frequency of meningioma-like tumors (72%) and a shorter latency (3.5 months)." (PMID 38571886, 2024). "TERT promoter mutations or homozygous deletion of cyclin-dependent kinase inhibitors A and B (CDKN2A/B) are molecular features of grade 3 meningiomas." (PMID 39202270, 2024). "Herein, we screened histologically defined grade 2 meningiomas and only found one TERT promoter mutation and one homozygous CDKN2A/B deletion during our molecular testing (< 1% of analyzed tumors)." (PMID 38720399, 2024). "In this study, we investigated the utility of MTAP and p16 IHC as surrogate markers of CDKN2A deletion in meningiomas." (PMID 39409918, 2024). "High-grade meningiomas often have frequent chromosomal aberrations, such as losses of 1p, 9p (CDKN2A/B), 10q, and 14q, and/or gains of 1q." (PMID 38730704, 2024). "MTAP immunostaining can be a good surrogate marker for identifying CDKN2A homozygous deletion in meningiomas." (PMID 39409918, 2024). "In this study, we evaluate the utility of evaluating p16 and MTAP expression by IHC as surrogate markers for homozygous deletion of CDKN2A/B in meningiomas." (PMID 39409918, 2024). "CDKN2A is crucial for cell cycle regulation, inhibiting cell proliferation, promoting apoptosis, and serving as a biomarker for invasive meningioma." (PMID 39519383, 2024). "This is clinically relevant given that homozygous deletion of CDKN2A/B is part of the criteria that determine the WHO grade of meningiomas under the most recent WHO Classification of CNS tumors." (PMID 39409918, 2024). "Among 41 meningiomas with intact CDKN2A, 22 of them showed p16 expression, 17 showed faint expression at institution 1, whereas at institution 2, 21 cases showed expression and 10 cases showed faint expression." (PMID 39409918, 2024). "The grade 1 meningioma (#19), which showed intact CDKN2A status by FISH, showed expression of MTAP when the antibody concentration was increased to a 1:100 dilution." (PMID 39409918, 2024). "In a resource-limited setting, screening morphologically grade 2 meningiomas with p16 immunohistochemistry can help identify a subset of cases to submit for additional CDKN2A assessment and possible change in grade." (PMID 36723772, 2023). "The results indicate that CDKN2A/B plays an important role in malignant meningioma and cell proliferation." (PMID 38017560, 2023). "According to the latest grading criteria, meningiomas should be classified as WHO grade 3 whenever telomerase reverse transcriptase (TERT) promoter mutations and/or cyclin-dependent kinase inhibitor 2 A/B(CDKN2A/B) pure deletions are present." (PMID 37529695, 2023).
meningioma (continued). "Further large-scale studies of WHO grade 2 and 3 meningiomas are needed to validate the importance of heterozygous CDKN2A/B deletions with consideration of established factors." (PMID 38017560, 2023). "CDKN2A encodes a cell cycle regulatory protein, and ongoing clinical trials are examining the role of CDK4/6 inhibition in meningioma." (PMID 36723772, 2023). "The 12-, 24-, and 60-month PFS rates for CDKN2A/B wild-type meningiomas were 94.7%, 86.4%, and 67.8%." (PMID 38017560, 2023). "The median time to meningioma progression in those with CDKN2A/B wild-type status combined with WHO grade 1 was 199.9 months and in those combined with WHO grade 2 was 78.0 months." (PMID 38017560, 2023). "We saw significant up-regulation of similar cell cycle pathways in meningiomas with CDKN2A deletions as we observed in CDKN2Ahigh tumors except these pathways generally centered around the G2M checkpoint/transition instead of the G1-S checkpoint." (PMID 37093270, 2023). "Within the Toronto cohort, MG4 (proliferative) meningiomas had the highest proportion of both CDKN2Ahigh (11/19, 58%) and CDKN2A homodel cases (3/5, 60%)." (PMID 37093270, 2023). "CDKN2A homodel has been extensively researched and validated as biomarker of biological aggressiveness in meningiomas." (PMID 37093270, 2023). "Although CDKN2Ahigh meningiomas and meningiomas with CDKN2A deletions (homodel/heterodel) were mutually exclusive groups in our study, they both had poor clinical outcomes." (PMID 37093270, 2023). "Against this backdrop, it is of paramount importance to remind that the prevalence of CDKN2A/B deletions was 29.0% among the WHO grade 3 meningiomas in the present meta-analysis." (PMID 38017560, 2023). "The median time to meningioma progression in the heterozygous CDKN2A/B deletion arm was 26.1 (95% CI 23.3–29.0) months, whereas in those with a homozygous CDKN2A/B deletion median PFS time was 11.0 (95% CI 8.6–13.3) months (p = 0.032)." (PMID 38017560, 2023). "Conversely, nearly one-third (29.0%) of WHO grade 3 meningiomas exhibit a deletion in the CDKN2A/B gene." (PMID 38017560, 2023). "Meningiomas harboring homozygous deletions of CDKN2A/B are characterized by high recurrence rates independently from WHO grade, DNA methylation class, sex, age and tumor location." (PMID 36181606, 2023). "In higher grade meningiomas, other genomic alterations with independent prognostic value have been reported, namely mutation of TERT promoter and deletions of CDKN2A/B." (PMID 37760490, 2023). "Whenever present, meningiomas with CDKN2A/B deletions had significantly poorer PFS compared to CDKN2A intact/wt cases." (PMID 37093270, 2023). "When we plotted the CDKN2A mRNA expression levels of CDKN2A intact/wt meningiomas based on each sample’s IHC score, we found that tumors with “3+” or diffuse p16 positivity on IHC had significantly higher CDKN2A mRNA expression compared to all other groups." (PMID 37093270, 2023). "The Cox proportional hazards regression model yielded a significant HR of 6.8 (95% CI 5.5–8.5, p < 0.00001) for hetero- or homozygous CDKN2A/B deletions regarding meningioma progression." (PMID 38017560, 2023). "Alterations of CDKN2A and CDKN2B were found more frequently in recurrent meningiomas and were associated with poor prognosis." (PMID 36661712, 2023). "The CDKN2A and BAP1 mutation seem to be associated with aggressive forms of meningioma, while the SMASRCE1 mutation is attributable to the onset of spinal meningiomas." (PMID 37760490, 2023). "The group of meningioma patients with a homozygous CDKN2A/B deletion had 12-, 24-, and 60-month PFS rates of 41.1%, 25.8%, and 11.1%." (PMID 38017560, 2023). "MCM2 + meningiomas displayed more frequent atypical features (prominent nucleoli, small cells with high nuclear-to-cytoplasmic ratio) and CDKN2A hemizygous deletion (HeDe) (P = 0.011)." (PMID 37014425, 2023).
meningioma (continued). "Our results further encourage future analyses of the predictive value of radiomics in meningiomas for other molecular alterations, e.g., methylation classes or homozygous CDKN2A/B deletions." (PMID 37686690, 2023). "In conclusion, the present meta-analysis is the first investigation using reconstructed individual patient data to analyze the impact of heterozygous or homozygous CDKN2A/B deletions on progression-free survival in meningiomas." (PMID 38017560, 2023). "As phosphorylation of Rb is a key nidus of control for cell cycle progression from G1 to S, we wanted to assess its phosphorylation status in meningiomas from each CDKN2A group." (PMID 37093270, 2023). "Publication of the WHO 2021 criteria has officially moved meningioma grading into the molecular era, with recognition of the independent prognostic implications of TERT promoter mutations and CDKN2A/B deletions." (PMID 37675219, 2023). "Similar to homodel cases, the majority of meningiomas with CDKN2A/B heterodel were WHO grade 2 (20/40, 50%) or 3 (13/40, 33%), and were uncommonly grade 1 cases (7/40, 17%)." (PMID 37093270, 2023). "CDKN2Alow meningiomas also had the longest PFS, significantly better than both CDKN2A homodel or heterodel cases and CDKN2Ahigh meningiomas." (PMID 37093270, 2023). "The distribution of CDKN2A/B deletion among the WHO grades suggests that this molecular alteration is associated with higher WHO grade and more aggressive meningiomas." (PMID 38017560, 2023). "Homozygous deletions in the cell cycle regulator genes CDKN2A and/or CDKN2B are often found in recurrent and progressive meningiomas and are associated with poor prognosis." (PMID 37675219, 2023). "Homozygous deletion (homodel) of CDKN2A/B specifically, now a diagnostic criterion for WHO grade 3 meningiomas was found in only 4.5% of all meningiomas (68/1506) and 25% of all WHO grade 3 cases (38/148) in our cohort." (PMID 37093270, 2023). "We explain this seemingly discordant finding by showing that WHO grade 1 meningiomas have low levels of CDKN2A expression while WHO grade 3 tumors have high levels of expression, unless they have CDKN2A homodel." (PMID 37093270, 2023). "While this marker is overall rare in meningiomas, its relationship to other CDKN2A alterations on a transcriptomic, epigenomic, and copy number level has not yet been determined." (PMID 37093270, 2023). "Despite the discordant and mutually exclusive status of the CDKN2A gene in these groups, both CDKN2Ahigh meningiomas and meningiomas with CDKN2A deletions were enriched for similar cell cycle pathways but at different checkpoints." (PMID 37093270, 2023). "Further large-scale trials of WHO grade 2 and 3 meningiomas investigating heterozygous CDKN2A/B deletions with consideration of extent of resection as well as adjuvant radiation therapy regimes have to be performed." (PMID 38017560, 2023). "The previously as WHO grade 2 classified meningiomas despite a homozygous CDKN2A/B deletion had a median time to meningioma progression of 9.0 months (95% CI 3.6–14.4)." (PMID 38017560, 2023). "Based on the results of the present meta-analysis, we are able to demonstrate that both homozygous and heterozygous CDKN2A/B deletions significantly shorten PFS in a large-scale meningioma cohort." (PMID 38017560, 2023). "We dichotomized CDKN2A intact meningiomas into CDKN2Ahigh and CDKN2Alow cases by selecting an unbiased cut-off that was agnostic to outcome and was reproducible in each cohort that used different RNAseq techniques." (PMID 37093270, 2023). "In this study, we assessed CDKN2A copy number variations as a requisite to exclude CNS WHO grade 3 meningioma." (PMID 37014425, 2023).